CCL5 (C-C motif chemokine ligand 5)
Diseases named in the same sentence as CCL5 in open-access papers (continued):
Sharing a sentence is not in itself a finding about the gene and the disease.
glomerular disease (3 papers, 2014 to 2025). "Our findings establish that CCL5 is upregulated in glomerular diseases in both human and mouse models." (PMID 40986444, 2025). "Rather than global CCL5 inhibition, selective CCR1/CCR5 antagonism in macrophages may preserve the podocyte-protective effects of CCL5 while mitigating its proinflammatory activity, offering a more refined therapeutic strategy for glomerular disease." (PMID 40986444, 2025). "However, CCL5 was upregulated in multiple human glomerular diseases, including FSGS, IgAN, and LN, suggesting broader clinical relevance." (PMID 40986444, 2025). "Quantitative analysis revealed significantly higher CCL5 intensity in FSGS, IgAN, and LN compared with MCD, and the degree of CCL5 and synaptopodin colocalization was also increased, suggesting upregulation of CCL5 in glomerular disease." (PMID 40986444, 2025).
glomerulosclerosis (3 papers, 2014 to 2025). A hardening of the kidney glomerulus caused by scarring of the blood vessels. "However, in adriamycin-induced nephropathy, CCL5 worsened glomerular injury, increasing proteinuria, glomerulosclerosis, and podocyte loss." (PMID 40986444, 2025). "Mice receiving Ccl5-deficient BM exhibited reduced albuminuria, less glomerulosclerosis, and higher WT-1+ podocyte counts, regardless of host genotype, suggesting that BM-derived CCL5 drives injury." (PMID 40986444, 2025). "In contrast, Ccl5-KO host mice exhibited more severe albuminuria, increased glomerulosclerosis, and fewer WT-1+ podocytes per glomerulus, regardless of BM donor type." (PMID 40986444, 2025).
graft versus host disease (3 papers, 2023 to 2025). An immune system disorder that occurs after allogeneic hematopoietic stem cell transplant and is a reaction of donor immune cells against host tissues. "In the studies presented above, CCL5 polymorphisms have been rather negative prognostic factors of the risk of developing graft versus host disease." (PMID 36983384, 2023).
hyperlipidemia (3 papers, 2020 to 2025). "In a hyperlipidemia model, CCL5 modulates NF-κB activation through the CCR5 receptor in smooth muscle cells." (PMID 39857418, 2025). "PPB treatment reduced VSMC proliferation and phenotype switching induced by hyperlipidemia through inhibition of the CCL5/CCR5 pathway." (PMID 32727125, 2020). "It has also been reported that the CCR5/CCL5 pathway is involved in the VSCM phenotype switching induced by hyperlipidemia." (PMID 32727125, 2020). "The CCL5/CCR5 pathway is involved in proliferation of VSMCs due to hyperlipidemia." (PMID 32727125, 2020). "In conclusion, our study showed that PPB reduced the upregulation of CCL5/CCR5 due to hyperlipidemia and decreased VSMC proliferation and phenotype switching which may accelerate vascular remodeling." (PMID 32727125, 2020). "Blocking CCL5/CCR5 signaling reduces body weight in obese mice and prevents hyperlipidemia-induced inflammatory atherosclerotic remodeling." (PMID 40725440, 2025). "The CCL5/CCR5 expression, VSMC proliferation and phenotypic alterations were evaluated using a cell model of VSMC exposed in hyperlipidemia, and an animal model of mice fed a high-fat-diet (HFD)." (PMID 32727125, 2020). "The expression of CCL5/CCR5 increased in both the cell and animal models of hyperlipidemia." (PMID 32727125, 2020).
latent infection (3 papers, 2009 to 2022). "In our model, CCL5 production was high during infection of naïve mice, remaining elevated during latent infection, but was drastically reduced when TKdel-primed mice were challenged with WT." (PMID 35590057, 2022). "This was in contrast to Tcf7+ cells from latent infection, which maintained relatively higher levels of Gzmm, Ifngr1, and Ccl5." (PMID 35185882, 2022).
Lyme disease (3 papers, 2016 to 2022). Lyme disease (named after the towns in the USA where the disease was first identified) is a bacterial infection caused by Borrelia burgdorferi. "For instance, in Lyme neuroborreliosis and Lyme arthritis CCL5 mRNA expression and production were increased following B. burgdorferi exposure." (PMID 36001729, 2022).
meningoencephalitis (3 papers, 2016 to 2025). Inflammation of the meninges and brain, generally secondary to an infectious cause. "In addition, increased CCL5 production was observed in patients with mild TBEV symptoms, even without intrathecal inflammation, whereas patients with TBEV-induced meningoencephalitis showed elevated CCL5 levels in the CSF, which correlated with pleocytosis." (PMID 40918112, 2025).
mycobacterial infection (3 papers, 2013 to 2022). "Among the molecules, chemokines (CCL3, CCL4, CCL5) and cytokines (IL6, IL1B) are known to induce M1 macrophage polarization in response to mycobacterial infection." (PMID 35821058, 2022). "Increased levels of chemokines, including CXCL5, CCL5 and CXCL1, were reported in previous mouse mycobacterial infection experiments." (PMID 29228045, 2017).
myositis (3 papers, 2014 to 2025). "Previous studies have also shown elevated muscle levels of numerous cytokines associated with type 1 inflammation, including CCL5, CXCL9, CXCL10, CXCL11, IFNG, and TNF in IBM patients compared to various myositis and non-myositis controls." (PMID 40034760, 2025). "In particular, chemokines, a class of small cytokines with potent chemotactic activity, such as IL-8 (CXCL8), Mig (CXCL9), IP-10 (CXCL10), RANTES (CCL5), and MCP-1 (CCL2), are overexpressed during myositis in infiltrating inflammatory cells, extracellular matrix, and muscle fibers." (PMID 24895631, 2014). "In order to move towards the role of myokines in the modulation of myositis pathology, we mention an in vitro study that demonstrated that overexpression of MHC I in C2C12 cell line myotubes led to the release of inflammatory chemokines CCL2 and CCL5 via the ER stress pathway." (PMID 32775472, 2020).
neurofibroma (3 papers, 2017 to 2021). An intraneural or extraneural neoplasm arising from nerve tissues and neural sheaths. "For example, Ccl5 expression is up-regulated only at day 4 after nerve injury (4.21x), yet expression persists in neurofibroma (4.56x)." (PMID 28256556, 2017). "In mouse neurofibroma, CCL5 is mainly expressed by macrophages and Schwann cells." (PMID 33413690, 2021). "Inhba, Cxcl2, Il1b, Clcf1, Lif, and Ccl5 were up-regulated in human neurofibroma SCs, and may justify further study." (PMID 28256556, 2017).
oral squamous cell carcinoma (3 papers, 2014 to 2024). "For instance, CXCL1, CXCL2, CXCL8, and CCL5 are all related to the progression and diagnosis of oral squamous cell carcinoma." (PMID 39199704, 2024). "In conclusion, our results suggest that 1 ng/ml rhBMP-2 may induce invasion of oral squamous cell carcinoma (OSCC) cells by CCL5 release in coculture models." (PMID 25271422, 2014). "In oral squamous cell carcinoma, RACK1 decreased IL-6, CCL5, and CSF levels and increased the M2/M1 ratio in an NF-κB axis-dependent manner." (PMID 38315284, 2024). "Moreover, oral squamous cell carcinoma cell lines, including HSC2, respond to inflammatory cytokines IL1β and TNFα with an increased chemokine expression, including CXCL1, CXCL2, CXCL8, and CCL5." (PMID 39199704, 2024). "Moreover, oral squamous cell carcinoma cell lines, including HSC2, respond to inflammatory cytokines IL1β and TNFα with an increased expression of chemokines such as CXCL1, CXCL2, CXCL8, and CCL5." (PMID 39199704, 2024).
osteonecrosis (3 papers, 2020 to 2024). A none disease characterized by death of bone tissue due to a lack of blood supply. "A decreased expression of some cytokines in cultured GD macrophages has been described for CCL5/RANTES and CXCR4, while the serum level of CCL5/RANTES is elevated in GD patients with osteonecrosis." (PMID 38667330, 2024).
pancreatic adenocarcinoma (3 papers, 2012 to 2018). "Evaluating the mechanism of pancreatic adenocarcinoma cell evasion from the immune system highlighted the importance of CCL5/CCR5 interaction." (PMID 29358632, 2018). "Having established the importance of CCR5/CCL5 signaling axis in various cancers, their role in metastasis of pancreatic adenocarcinoma remains unknown." (PMID 29358632, 2018). "We note that disruption of the Ccl5/Ccr5 axis in a model of pancreatic adenocarcinoma results in reduced intra-tumoral Tregs and slows tumor growth, implying that FAK-dependent regulation of this paracrine signaling axis may be more generally important." (PMID 26406376, 2015).
pemphigus (3 papers, 2017 to 2022). Pemphigus is a group of rare autoimmune diseases that cause blistering of the skin and mucous membranes (mouth, nose, throat, eyes, and genitals).This conditioncan occur at any age, but often strikes people in middle or older age. "We found that genes enriched in localized human pemphigus foliaceous compared to pemphigus vulgaris, including CCL5 and CYP1B1 were also captured in the canine DEGs when examined by two-tailed student's t-tests." (PMID 34660634, 2021). "CCL5 and CCL20 were found to be highly expressed in pemphigus lesions." (PMID 35449056, 2022).
pituitary tumor (3 papers, 2019 to 2024). A benign or malignant neoplasm affecting the pituitary gland. "AIP-mutation positive pituitary tumors were associated with an altered tumor microenvironment including increased CD86+ macrophage and FOXP3+ Tregs infiltration, and upregulation of tumor-derived cytokine CCL5 (also known as RANTES)." (PMID 38479600, 2024). "Further studies will be needed to reveal the functional role of FOXP3 in pituitary tumors and to see whether CCL5 is indeed involved in recruitment of T-reg cells in AIPpos pituitary tumors." (PMID 30867568, 2019).
preeclampsia (3 papers, 2015 to 2022). Preeclampsia is a hypertensive disorder of pregnancy that is characterized by new-onset hypertension with proteinuria presenting after 20 weeks of gestation, and depending on mild or severe forms may initially present with severe headache, visual disturbances, and hyperreflexia. "No significant findings have been detected, except from a trend toward higher placental CD68+ cells (P = 0.07) and HGF (P = 0.06) in preterm placentas and to higher CCL5 in patients with preeclampsia (P = 0.07)." (PMID 33313931, 2021).
primary Sjögren’s syndrome (3 papers, 2021 to 2025). "Here we demonstrate the transcriptome of CCR9-expressing pathogenic T helper cells from primary Sjögren’s syndrome patients and healthy controls and identify CCL5 as a novel effector molecule of CCR9+ Th cells." (PMID 34386009, 2021). "CCL5 production was particularly associated with effector CD8 + T cells and could be triggered by activation with autoantigens in primary sjogren’s syndrome, suggesting this mechanism may similarly be occurring in AIH." (PMID 41343465, 2025). "Increased CCL5 expression and CD8 T cells have been shown to be pivotal regulators of immunopathology in primary Sjögren’s syndrome (pSS) and pSS-like disease." (PMID 35720379, 2022).
renal carcinoma (3 papers, 2020 to 2024). A carcinoma arising from the epithelium of the renal parenchyma or the renal pelvis. "This study investigated C–C motif chemokine ligand 5 (CCL5)'s tumorigenic impact on renal cancer cells and CTCs using bioinformatics, in vivo, and in vitro experiments." (PMID 39227943, 2024). "In order to further examine the biological function of CCL5 on mast cell recruitment in renal carcinoma, CCL5 was knocked down in 786-O and Caki-1." (PMID 33177244, 2020). "We hypothesized that CCL5 promoted the EMT process in renal cancer cells, which in turn impacted CTCs and ultimately led to a poor prognosis." (PMID 39227943, 2024). "CCL5 exhibited high expression in various CTCs, correlating with poor prognosis in renal cancer." (PMID 39227943, 2024). "In renal cancer, CCL5 was highly expressed in tumor tissues and correlated with a poor prognosis." (PMID 39227943, 2024). "Therefore, we further validated the role of CCL5 in EMT using renal cancer cells." (PMID 39227943, 2024). "Thus, we proposed that CCL5 might be overexpressed in renal cancer CTCs and might enhance the malignant phenotype of the cells." (PMID 39227943, 2024). "Our findings confirmed that the C–C motif chemokine ligand 5 (CCL5) can stimulate EMT and foster the malignant phenotypes of renal cancer cells through the smad pathway." (PMID 39227943, 2024). "In the common renal carcinoma cell lines 786-O and CAKI-2 that we tested, CCL5 showed higher expression in CAKI-2 and lower in 786-O." (PMID 39227943, 2024). "We established the renal cancer circulating tumor cell line 786-O-CTC and investigated the effect of CCL5 on its invasive phenotype." (PMID 39227943, 2024).
scleroderma (3 papers, 2017 to 2023). Scleroderma is a rare autoimmune connective tissue disorder characterized by abnormal hardening of the skin and, sometimes, other organs. "The early expression of CCL2, CCL3 and CCL5 is also observed in a mouse model of scleroderma, with a subsequent rapid reduction of CCL5 and maintained high expression of CCL2 and CCL3." (PMID 33313931, 2021).
seminoma (3 papers, 2023 to 2026). A radiosensitive malignant germ cell tumor found in the testis (especially undescended), and extragonadal sites (anterior mediastinum and pineal gland). "Moreover, seminoma displayed high expression of genes associated with innate immune response, regulation of B cell activation (e.g., CCL5, APOE, MIF, NOP53), suggesting that the immune activity in TME play a role in tumorigenesis." (PMID 38123589, 2023).
systemic sclerosis (3 papers, 2020 to 2025). A chronic disorder, possibly autoimmune, marked by excessive production of collagen which results in hardening and thickening of body tissues. "When compared with NL and NXG fibroblasts, systemic sclerosis lesional fibroblasts showed a more modest upregulation of CCL5 and CXCL9." (PMID 39989459, 2025). "Thus, to compare the expression of NKG7 and CCL5 in systemic sclerosis versus healthy skin, systemic sclerosis T cells were binned together and compared as a group to healthy skin–derived T cells." (PMID 39989459, 2025). "This analysis revealed that there was no significant and meaningful (fold change [FC] > 2) upregulation in the expression of SPP1, CCL4, CCL5, and CXCL9 in systemic sclerosis myeloid cells." (PMID 39989459, 2025). "This points to an inflammatory gene expression signature in the skin that is reminiscent of that seen in systemic sclerosis, since IL6, CCL2, and CCL5 are elevated in the serum of patients." (PMID 31917819, 2020). "This analysis revealed that there was no meaningful difference in the NKG7 or CCL5 expression in systemic sclerosis T cells versus healthy T cells; in fact, their expression was slightly lower." (PMID 39989459, 2025). "Similarly, in systemic sclerosis (skin fibrosis), the levels of circulating CCL2, CCL3, and CCL5 chemokines were significantly higher in patients with systemic sclerosis than in controls." (PMID 33519923, 2020). "Unlike NL-specific fibroblasts, these systemic sclerosis-enriched fibroblast clusters did not overexpress IL32, CCL5, or CXCL9." (PMID 39989459, 2025).
acute myeloid leukemia (2 papers, 2020). Acute myeloid leukemia (AML) is a group of neoplasms arising from precursor cells committed to the myeloid cell-line differentiation. "The CCL5/CCR5 axis exerts profound effects on the progression of acute myeloid leukemia (AML)." (PMID 32630699, 2020).
Airway obstruction (2 papers, 2005 to 2023). Obstruction of conducting airways of the lung. "CCL5 is a chemoattractant cytokine that strongly attracts eosinophils, and eosinophilic inflammation is widely known to lead to airway obstruction in patients infected with RSV." (PMID 37755895, 2023).
alcoholic liver diseases (2 papers, 2010 to 2021). A disorder caused by damage to the liver parenchyma due to alcohol consumption. "Alcoholic liver disease patients have increased levels of hepatic RANTES/CCL5." (PMID 21331379, 2010).
aortic valve stenosis (2 papers, 2016 to 2022). Aortic valve stenosis (AVS) is a condition characterized by narrowing of the heart's aortic valve opening. "In patients with initially moderate DAS, DAS progression to severe aortic valve stenosis showed association with RANTES/CCL5 (p = 0.01), but not with other serum or VS biomarkers." (PMID 35735822, 2022).
Atherosclerotic lesion (2 papers, 2011 to 2023). A lesion associated with atherosclerosis, a multifactorial and multipart progressive disease manifested by the focal development within the arterial wall of lesions, that ranges from the development of a fatty streak, plaque progression, and plaque disruption. "On the other hand, CCL5 (RANTES) is secreted by activated platelets and ECs and interacts with several receptors (CCR1, CCR3, CCR5), mediating monocyte/macrophage infiltration in atherosclerotic lesions." (PMID 37175617, 2023).
atrial fibrillation (2 papers, 2018 to 2023). A disorder characterized by an electrocardiographic finding of a supraventricular arrhythmia characterized by the replacement of consistent P waves by rapid oscillations or fibrillatory waves that vary in size, shape and timing and are accompanied by an irregular ventricular response. "Furthermore, increased levels of CCL5, IL-1β, TNF-α, IFN-γ, IL-9, G-CSF, and GM-CSF were observed only in the atrial fibrillation patient, when compared to other Zika patients." (PMID 29370812, 2018). "In general, the results revealed that the ZIKV-infected patient with atrial fibrillation presented a typical serum biomarker storm already reported for ZIKV-infected patients, with a more prominent pro-inflammatory status mediated by CCL5, IL-1β, TNF-α, and IFN-γ." (PMID 29370812, 2018).
bacterial vaginosis (2 papers, 2011 to 2021). Infection caused by bacterial overgrowth in the vagina. "Indeed, bacterial vaginosis has been associated with increased levels of IL-1 beta, IL-6, IL-8, IL-10 and TNF-alpha, RANTES (CCL5), macrophage inflammatory protein (MIP-1 alpha/CCL3) and MIP-1 beta (CCL4) in genital samples." (PMID 21966450, 2011).
biliary atresia (2 papers, 2022 to 2023). A rare, biliary tract disease characterized by progressive obliterative cholangiopathy of the intra- and extrahepatic bile ducts, occurring in the embryonic/ perinatal period, leading to severe and persistent neonatal jaundice and acholic stool. "It has been suggested that the expression of CCL3 and CCL5 are elevated in a time-dependent manner until seven days, indicating that these two molecules are crucial for the pathogenesis of biliary atresia in mice." (PMID 35204421, 2022). "They observed that TLR3 signaling led to the expression of CCL5 via NF-κB and IRF3 in bile duct cells, and they suggested the involvement of this signaling pathway in biliary atresia pathogenesis." (PMID 37511764, 2023).
bladder tumor (2 papers, 2015 to 2022). "We observed that bladder tumors uniformly expressed only low levels of CTL attracting chemokines: CCL5, CXCL9, and CXCL10 (respective ligands for CTL-expressed CCR5 and CXCR3)." (PMID 25806105, 2015).